IGF2R (insulin like growth factor 2 receptor)
Diseases named in the same sentence as IGF2R in open-access papers (continued):
Sharing a sentence is not in itself a finding about the gene and the disease.
infection (11 papers, 2004 to 2023). The state of being infected such as from the introduction of a foreign agent such as serum, vaccine, antigenic substance or organism. "While IGF2R primarily localized to the perinuclear region in uninfected cells, early in infection (24 hpi) it developed a less polarized phenotype." (PMID 32041945, 2020). "Altogether with our Tm data, these results suggest the regulation of IGF2R at both early and late stages of infection." (PMID 32041945, 2020). "As IGF2R had altered Tm values at all infection time points, we monitored its localization throughout infection." (PMID 32041945, 2020). "Additionally, several host proteins including CD63, TGN46, CI-M6PR/IGF2R and TFR have been reported as vAC residents during infection." (PMID 32910773, 2020). "During the initiation and propagation stages of infection, several renin-angiotensin system (RAS) family genes (e.g., ACE2 and ANPEP) are upregulated, whereas others (e.g., epidermal growth factor receptor - EGFR and insulin-like growth factor 2 receptor - IGF2R) are downregulated." (PMID 38813031, 2023).
neurodegenerative disease (5 papers, 2020 to 2025). A disorder of the central nervous system characterized by gradual and progressive loss of neural tissue and neurologic function. "IGF-2R, in fact, plays a key role in long-term memory, and its activation by several ligands shows beneficial effects in multiple neurodevelopmental and neurodegenerative disease models." (PMID 41725679, 2025). "Seven genes were observed to be involved in both infections of three coronaviruses and two neurodegenerative diseases, including the HSP90AA1, ALDH2, CAV1, COMT, MTOR, IGF2R and HSPA1A." (PMID 37015947, 2023). "Analogs of IGF2, with selective binding to IGF2R and suppressed affinity for “mitogenic” IGF1R and IR-A, could be important in the treatment of neurodegenerative diseases." (PMID 32877466, 2020). "Regarding the recently discovered importance of the IGF2:IGF2R interactions in the central nervous system, our new method could find applications in the development of IGF2 analogs, which could be clinically important in the treatment of some neurodegenerative diseases." (PMID 32877466, 2020).
heart diseases (2 papers, 2015 to 2016). "CREB, as a transcriptional repressor, binds to the IGF2R promoter region and further protects against hypoxia-induced heart disease." (PMID 26610485, 2015).
cardiovascular diseases (1 paper, 2023). "Different from the high expression of IGF-2 in cardiovascular diseases, and IGF2R also has low expression in cardiovascular diseases." (PMID 37063954, 2023).
neurological disorders (1 paper, 2020). "The assay will be helpful for the characterization of new IGF2 mutants to study the functions of IGF2R and the development of new compounds for the treatment of neurological disorders." (PMID 32877466, 2020).
psychiatric disorder (1 paper, 2023). A disorder characterized by behavioral and/or psychological abnormalities, often accompanied by physical symptoms. "From our perspective, the study of IGF-2 is interesting in the context of psychiatric disorders because IGF-2 can trigger IGF-1R signaling, as well as IGF-2R signaling, whereby IGF-2 binding may act as a memory enhancer and a pro-cognitive agent through the induction of neurogenesis." (PMID 37894932, 2023).
IGF2R also shares sentences with these, for which no sentence is quoted: breast tumor (3 papers); endometrial cancer (3); glioblastoma (3); triple-negative breast carcinoma (3); adrenocortical carcinomas (2); Batten disease (2); gastric tumors (2); Hypertension (2); hypertrophy (2); metabolic disease (2); adenocarcinoma (1); adrenocortical adenomas (1); adrenocortical tumor (1); anaplastic astrocytoma (1); ankylosing spondylitis (1); Anxiety (1); autoimmune disease (1); bacterial infection (1); bipolar disorder (1); Cerebral ischemia (1); cervical tumors (1); chronic kidney failure (1); colon adenocarcinoma (1); Cryptococcal meningitis (1); cryptococcosis (1); dementia (1); Dent disease (1); diabetic cardiomyopathy (1); ductal carcinoma in situ of the breast (1); endometrioid adenocarcinoma (1).
A further 25 diseases each share a sentence with IGF2R in 1 paper.